HSF1 (heat shock transcription factor 1)
Diseases named in the same sentence as HSF1 in open-access papers (continued):
Sharing a sentence is not in itself a finding about the gene and the disease.
hepatocellular carcinoma (47 papers, 2013 to 2026). A malignant tumor that arises from hepatocytes. "Elevated S326 phosphorylation of HSF1 was also significantly associated with the progression, invasion, and prognosis of hepatocellular carcinoma." (PMID 34239690, 2021). "Heat-shock factor 1 (HSF1) is a multifunctional transcription factor whose overexpression is associated with the development, progression, and aggressiveness of several tumor types, including hepatocellular carcinoma (HCC)." (PMID 41898642, 2026). "In liver cancer, HSF1 upregulation has been found to correlate with tumor invasion and metastasis, as well as with patients’ prognosis, in hepatocellular carcinoma (HCC)." (PMID 39243039, 2024). "In the context of hepatocellular cancer cells, downregulating HSF1 reduces proliferative and anti-apoptotic abilities of tumor cells." (PMID 38748048, 2024). "HSF1 also serves as a prognostic biomarker in endometrial cancer, hepatocellular carcinoma (HCC), esophageal carcinomas, and oral squamous cell carcinoma (OSCC)." (PMID 38339390, 2024). "In hepatocellular carcinoma cells (HCCs) for example, microRNA-644a (miR-644a) downregulates HSF1 by binding to its 3'-untranslated region, promoting an inhibition of proliferation and the onset of apoptosis." (PMID 37153737, 2023). "Further, HSF1 inhibition downregulates mevalonate and cholesterol biosynthesis-related gene expression in hepatocellular carcinoma." (PMID 37153737, 2023). "HSF1 participates in the initiation, development, and progression of various cancers, including hepatocellular carcinoma." (PMID 36557005, 2022). "The highest frequency of HSF1 gene amplification is found in ovarian, pancreatic, breast and liver carcinomas which also show elevated mRNA levels of HSF1." (PMID 35311075, 2022). "HSF1 ability to promote migration and invasion was demonstrated in hepatocellular carcinoma, melanoma, breast, ovarian and pancreatic cancers." (PMID 34198675, 2021). "Many studies indicated that cell motility for invasion and migration is promoted upon high expression of HSF1 in various cancer cells, such as breast cancer, hepatocellular cancer, and ovarian cancer." (PMID 34064083, 2021). "In hepatocellular carcinoma cells, HSF1 modulates E-Cadherin expression through directly regulating Snail1 transcription." (PMID 31752429, 2019). "Clinical relevance for HSF1 was demonstrated in breast, lung, and hepatocellular carcinoma where high mRNA and/or protein expression correlates with poor prognosis." (PMID 30131848, 2018). "HSF1 is elevated in breast, colon, lung and hepatocellular cancers, and activated or elevated HSF1 often couples with poor cancer prognosis." (PMID 27997575, 2016). "We thus queried the only available human HSF1 ChIP-Seq data set, derived from the hepatocellular carcinoma cell line HepG2." (PMID 26631063, 2015). "Conversely, HSF1 activation promotes growth of premalignant cells and hepatocellular carcinoma development by stimulating lipid biosynthesis and perpetuating chronic hepatic metabolic disease induced by carcinogens." (PMID 24467529, 2014). "The expression of HSF1 was measured by immunohistochemistry (IHC) in hepatocellular carcinomas (50 Hep B virus positive cases, 2 cores/case)." (PMID 23615731, 2013). "Similarly, in hepatocellular carcinoma, HSF1 has been reported to upregulate PD-L1 expression by inducing APOJ expression and activating the STAT3 signaling pathway." (PMID 40675964, 2025). "Furthermore, it has been demonstrated that HSF1 produced by hepatocellular carcinoma cells promotes the functional crosstalk of tumor cells with TAM." (PMID 39243039, 2024). "Additionally, several experimental models have demonstrated that a high level of HSF1 was required for EMT associated with the invasion and migration of human pancreatic cancer cells or hepatocellular carcinoma cells." (PMID 37894333, 2023). "HSF1 is also known to be involved in metabolic regulation in hepatocellular carcinoma." (PMID 36765939, 2023).
hepatocellular carcinoma (continued). "In addition, decreased triglyceride (TG) and cholesterol in blood and the liver tissue in hepatic steatosis and hepatocellular carcinoma models have been observed in HSF1 knock-out mice." (PMID 31540279, 2019). "In accordance, enhanced HSF1 mRNA expression has been detected in breast and hepatocellular carcinoma and enhanced nuclear HSF1 protein expression in a wide range of malignancies including hepatocellular carcinoma, breast, cervical, lung, pancreas, colon, and mesenchymal tumors." (PMID 30131848, 2018). "Previous studies have reported that the activation of HSF1 promoted the growth of hepatocellular carcinoma by stimulating lipid biosynthesis and activating the nuclear factor kappa B (NF‐κB) signaling pathway and mitogen‐activated protein kinase (MAPK) signaling pathway." (PMID 28783244, 2017). "Out of the 33 TCGA datasets, eight studies were found to be enriched by HSF1-CanSig 8q genes: adrenocortical carcinoma, colon adenocarcinoma, esophageal carcinoma, kidney chromophobe, hepatocellular carcinoma, lung adenocarcinoma, ovarian serous cystadenocarcinoma, and stomach adenocarcinoma." (PMID 29268782, 2017). "Notably, HSF1 activity correlates with a higher rate of survival in several cancer types: breast, lung, prostate, colon, myeloma, pancreas and hepatocellular carcinoma." (PMID 34198675, 2021). "Subsequently, the presence of HSF1 has been shown to induce tumor growth, invasion, and metastasis in melanoma and hepatocellular carcinoma (HCC)." (PMID 34064083, 2021). "It had been found that ablation of HSF1 restrains the growth of c-Myc-derived mouse hepatocellular carcinoma (HCC) cell lines, where it can downregulate of c-Myc levels." (PMID 29898735, 2018). "We found that ablation of HSF1 restrains the growth of c-Myc-derived mouse hepatocellular carcinoma (HCC) cell lines, where it induces downregulation of c-Myc levels." (PMID 29207593, 2017). "In addition, a study has demonstrated that high expression of HSF1 in peritumoral tissue but not in hepatocellular carcinoma tissue was associated with poorer survival and shorter time to recurrence." (PMID 26511079, 2015). "In hepatocellular carcinoma (HCC) tissues, HSAL3 is upregulated and activated by the TF HSF1 through its SE, which, in turn, interferes with the negative regulation of NOTCH signalling." (PMID 39690143, 2024). "Some reports indicate that HSF1 activation leads to the progression of NAFLD and, in the end, to hepatocellular carcinoma by stimulating lipid biosynthesis." (PMID 36359900, 2022). "Recently, HSF1 depletion in HLE and HLF hepatoma cells was reported to result in enhanced apoptosis, reduced proliferation, lipid depletion, and decreased glycolysis." (PMID 32408596, 2020). "From the standpoint of therapeutic applications for hepatocellular carcinoma (HCC) treatment, HSF1 inhibition was shown to sensitize the antiproliferative effects of simvastatin in HCC cells." (PMID 31540279, 2019). "For this purpose, the HSF1 gene expression was knocked-down in HLE and HLF hepatoma cells with specific small interfering RNA (siRNA)." (PMID 28903330, 2017). "The increased sensitivity of hepatocellular carcinoma and melanoma cell lines to HSP90 inhibition with HSF1 knocked down in vitro, illustrates the therapeutic potential of an HSF1 inhibitor in combination with HSP90 inhibition." (PMID 24675290, 2014). "Interestingly, HSF1 is highly expressed in hepatocellular carcinoma (HCC) patient samples and HCC is sensitive to combinational treatment, indicating a potential indication for the combinational treatment." (PMID 23615731, 2013).
hepatocellular carcinoma (continued). "We found that knockdown of HSF1 sensitizes cancer cells to HSP90 inhibitors in many different cancer lineages, including melanoma (A375, A2058), hepatocellular carcinoma (Hep3B, Huh7) and colon cancer (HCT116)." (PMID 23615731, 2013). "Furthermore, reduced mRNA levels associated with lipogenesis (fas, acc, and scd1) and lipogenic factors (srebp1c, pparγ1, pparγ2, and c/ebpβ) were observed in diethylnitrosamine (DEN)-induced hepatic steatosis and hepatocellular carcinoma (HCC) model-driven HSF1 knock-out mice." (PMID 31540279, 2019). "In addition, the suppression of lipogenesis and cholesterol metabolism by HSF1 suppression in an AKT and c-MYC-driven hepatocellular carcinoma model has been observed." (PMID 31540279, 2019). "In the present study, we presented the HSF1‐MYCN regulatory axis, a transcription‐dependent regulatory axis, to reveal the molecular mechanism of Hepatocellular Carcinoma (HCC) proliferation." (PMID 39248163, 2024). "Another report has shown that HSF1 upregulates the expression of ATG4B in hepatoma carcinoma cells by binding to the promoter region of the gene and consequently enhancing the epirubicin (EPI)-induced protective autophagy, which in turn promotes hepatocellular carcinoma (HCC) cell survival." (PMID 36598250, 2023). "Upregulation of the heat shock transcription factor 1 (HSF1) has been described as a frequent event in many cancer types, but its oncogenic role in hepatocellular carcinoma (HCC) remains poorly delineated." (PMID 28903330, 2017). "However, the specific roles of HSFs in hepatocellular carcinoma (HCC) have yet to be fully elucidated.Aims:To explore the involvement of the HSF family, particularly HSF1, in the progression and prognosis of HCC." (PMID 39248163, 2024).
melanoma (36 papers, 2011 to 2025). A malignant, usually aggressive tumor composed of atypical, neoplastic melanocytes. "Recently, increasing evidence highlighted a role for HSF1 in the modulation of tumor microenvironment and specifically of cancer-associated fibroblasts (CAFs) in many human tumors such as melanoma, lung, colon, breast, and prostate carcinomas." (PMID 34198675, 2021). "The failure of HSF1 ubiquitination by the ubiquitin ligase F-box/WD repeat-containing protein 7 α (FBXW7α) caused HSF1 accumulation and subsequent enhancement of the invasive and metastatic potential in human melanoma cells." (PMID 32268506, 2020). "In most cancers, including melanoma, FBXW7α is mutated or downregulated resulting in impaired degradation of HSF1, which increased the accumulation HSF1, thus, enhancing the metastatic potential of human melanoma." (PMID 30791487, 2019). "One of the genes in the signature, HSF1 has been already shown to be associated with early stage melanoma and has been shown to drive metastasis." (PMID 31673075, 2019). "Moreover, in another study, FBXW7α deficiency leads to HSF1 (Heat shock factor 1) accumulation and subsequent activation of the invasion-supportive transcriptional program and metastatic potential of human melanoma cells." (PMID 36901733, 2023). "Furthermore, MEK inhibition in these BRAFV600E mutant melanoma cells, caused HSF1 inactivation, protein destabilization, and aggregation that lead to melanoma cell demise by excessive proteotoxic stress." (PMID 27896217, 2016). "In concordance with the importance and increased expressions of HSF1 in cancer, the silencing of HSF1 led to a significant decrease in the proliferative capability in human melanoma cells." (PMID 40287736, 2025). "Overexpression of HSF1, on the other hand, exacerbated pro-invasive and migration capabilities of melanoma xenografts in vivo." (PMID 40287736, 2025). "In particular, HSF1 has been shown to upregulate the expression of the MDR1 gene, and HSF1 overexpression indeed promoted efflux activity and induced resistance to doxorubicin and paclitaxel in melanoma cells in vitro." (PMID 38730681, 2024). "dataset, we identified the ‘Regulation of HSF1‐mediated heat shock response’ pathway, which is related to the human melanoma phenotype." (PMID 38683133, 2024). "Another phosphorylation site on S419 was found at higher levels on melanoma cell lines, and the substitution of HSF1-Ser419 reduced the proliferation of these melanoma cell lines." (PMID 39433125, 2024). "The expression of the ABCB1 gene was found to be primarily dependent on HSF1 in all tested doxorubicin- and paclitaxel-resistant melanoma cell lines." (PMID 37958341, 2023). "Existing evidence has shown that FBXW7α is a well-known ubiquitinating enemy of HSF1, and FBXW7 deficiency promotes HSF1 accumulation in melanoma cells and enhances their metastatic ability." (PMID 37686660, 2023). "It is important to note that proliferation reduction rates by HSF1 KD in melanoma cell lines were the highest among those in other types of cancer cell lines." (PMID 35906200, 2022). "The correlation between HSF1 expression and metastatic potential has been reported in breast, colon, lung, prostate, hepatocellular tumors and malignant melanoma, indicating that HSF1 supports anchorage–independent growth." (PMID 36069792, 2022). "The upregulation of HSF1 in melanoma likely resulted from its inefficient degradation due to frequent mutations or downregulation of the ubiquitin ligase FBXW7α." (PMID 35311075, 2022). "For example, HSF1 essentiality in AML and melanoma is tightly linked with a protein synthesis phenotype, consistent with a previous report detailing how protein synthesis rates are coupled with HSF1 activation." (PMID 33328249, 2021).
melanoma (continued). "For example, hyperthermic perfusion of limbs with melphalane and TNF-α has been employed to reduce tumor burden in unresectable limb sarcoma or melanoma, perhaps by mitigating thermoresistance through the downregulation of HSF1-regulated HSPs." (PMID 31814876, 2019). "Down-regulation of HSF1 in human melanoma MeWo cells with the aid of specific shRNA was associated with arrest of cell cycle on G1 phase whereas TPL and another HSF1 inhibitor, phenethyl isothocyonate, induced G2/M cell cycle arrest in cancer cells." (PMID 29930764, 2018). "In line with this, another study observed an indispensable role of HSF1 in melanoma progression and migration, thus highlighting its potential as therapeutic target in melanoma." (PMID 27896217, 2016). "HSF1 knockdown in the melanoma cell line MeWo enhances its sensitivity to heat shock but not to DTIC toxicity." (PMID 27045471, 2016). "HSF1 has also been identified as one of the only six potent metastasis-promoting genes in a genome-wide screen for enhancers of invasion by malignant melanoma cells." (PMID 24467529, 2014). "On the other hand, in mouse melanoma cells expressing constitutively active HSF1, an enhanced mobility and more dynamic anchorage-independent growth was observed." (PMID 24467529, 2014). "In the presented work, we screened the sensitivity of mouse (B16F10) and human (WM793B and 1205Lu) melanoma cells overexpressing HSF1 to different anticancer drugs." (PMID 24165036, 2013). "To further investigate the mechanism of HSF1-dependent resistance of melanoma cells to doxorubicin we tested two mutant forms of HSF1: constitutively active one and dominant-negative one." (PMID 24165036, 2013). "Melanoma cells expressing transcriptionally competent and constitutively active HSF1 mutant characterized by an enhanced expression of HSPs did not acquire resistance." (PMID 24165036, 2013). "The results of our study indicate that melanoma cells with HSF1 overexpression are more resistant to doxorubicin or paclitaxel." (PMID 24165036, 2013). "Here, we generated melanoma cells with different mutant forms of human HSF1, leading either to constitutive HSPs activation (transcriptionally active) or lacking the ability to activate HSPs expression (dominant-negative)." (PMID 24165036, 2013). "HSF1 overexpression facilitates the survival of melanoma cells treated with doxorubicin or paclitaxel." (PMID 24165036, 2013). "In this study, we established mouse and human melanoma cells overexpressing hHSF1 to study the effect of HSF1 on the survival of cancer cells treated with cytotoxic agents used in chemotherapy." (PMID 24165036, 2013). "We constructed mouse (B16F10) and human (1205Lu, WM793B) melanoma cells overexpressing full or mutant form of human HSF1: a constitutively active one with a deletion in regulatory domain or a dominant negative one with a deletion in the activation domain." (PMID 24165036, 2013). "We were thus able to evaluate the contribution of HSF1 and HSPs level in the development of drug resistance by melanoma cells." (PMID 24165036, 2013). "We analyzed the expression of several ABC transporters in melanoma cells having different HSF1 status." (PMID 24165036, 2013). "The expression of Abcb1b/ABCB1 gene was mostly dependent on HSF1 in all three tested melanoma cell lines." (PMID 24165036, 2013). "Down-regulation of HSF1 decreased cell proliferation and enhanced sensitivity to hyperthermia in human melanoma cell lines." (PMID 22152097, 2011). "Interestingly, HSF1 pSer419 is related to the proliferation of melanoma cells, promoting tumor formation." (PMID 37153737, 2023). "In melanoma cells with HSF1 overexpression, upregulation of ABCB1 gene transcription was prominent." (PMID 37958341, 2023). "While there were no data on the role of HSPB7 in melanoma, HSF1 was shown to be upregulated in melanoma due to the loss of FBX7, and was shown to be involved in regulating the metastatic potential." (PMID 35269844, 2022).